CCN5 (cellular communication network factor 5)
Diseases named in the same sentence as CCN5 in open-access papers (continued):
Sharing a sentence is not in itself a finding about the gene and the disease.
invasive carcinoma (2 papers, 2024 to 2025). A carcinoma that is not confined to the epithelium, and has spread to the surrounding stroma. "CCN5 and ER showed low expression in normal breast tissue and invasive carcinoma tissue, but high expression in DCIS tissue." (PMID 40016720, 2025). "The correlation between expression of CCN5 and ER in different tissues and also differences in expression in invasive carcinoma were analysed." (PMID 40016720, 2025). "In advanced BC, the positive expression rates of CCN5 and ER in invasive carcinoma were 39.22% (51/130) and 36.92% (48/130) respectively, while the negative expression rates were 60.77% (79/130) and 63.08% (82/130) respectively." (PMID 40016720, 2025). "The correlation between CCN5 and ER expressions in different tissues and their differential expression in invasive carcinoma were also examined." (PMID 40016720, 2025). "CCN5 and ER had low expression in normal breast tissues and invasive carcinoma tissues, but high expression in DCIS, with this difference being statistically significant (X2 = 119.899, P < 0.001; X2 = 113.524, P < 0.001, respectively)." (PMID 40016720, 2025). "The expression of CCN5 and ER in BC showed a positive correlation in normal breast tissue (rs = 0.014, P = 0.827), DCIS tissue (rs = 0.046, P = 0.461), and invasive carcinoma tissue (rs = 0.024, P = 0.703)." (PMID 40016720, 2025). "The current study showed a positive correlation in the expression of CCN5 and ER across normal breast tissue, DCIS tissue, and invasive carcinoma tissue." (PMID 40016720, 2025). "In this study on 130 cases of advanced BC, CCN5 and ER were expressed in normal breast tissue, DCIS tissue, and invasive carcinoma tissue, with CCN5 showing a low–high-low expression pattern." (PMID 40016720, 2025).
lymph node metastases (2 papers, 2024 to 2025). "Moreover, patients without lymph node metastases exhibited significantly higher expression levels of both CCN5 and E-cadherin compared with those with lymph node metastases, suggesting a potential association between these proteins and metastatic spread." (PMID 39144722, 2024). "Among patients with lymph node metastases, six out of 19 (31.58%) expressed CCN5 positively, compared to 25 out of 33 (75.76%) in patients without lymph node metastases." (PMID 39144722, 2024). "Specifically, the higher expression levels of CCN5 and E-cadherin in primary lesions and their lower expression levels in recurrent lesions and tissues with lymph node metastases may assist clinicians to identify patients who are at the higher risk of recurrence and metastasis." (PMID 39144722, 2024). "Patients without lymph node metastases exhibited significantly higher expression levels of CCN5 and E-cadherin compared with those with lymph node metastases (Χ2 = 9.775, Χ2 = 9.1479, p < 0.05)." (PMID 39144722, 2024). "Besides, the CCN5 expression in the group without lymph node metastases was higher than that in the group with lymph node metastases." (PMID 39144722, 2024).
metabolic syndrome (2 papers, 2018 to 2024). A cluster of metabolic risk factors for CARDIOVASCULAR DISEASES and TYPE 2 DIABETES MELLITUS. "CCN5/WISP2 limits adipocyte differentiation in abdominal subcutaneous adipose tissue; reduced expression is linked to adipose hypertrophy associated with metabolic syndrome, while overexpression increases insulin sensitivity and is protective against metabolic syndrome." (PMID 39401200, 2024). "CCN5/WISP2 transcriptional activation is higher in subcutaneous adipose tissue compared to visceral tissue and also higher in the adipose tissue in equally obese individuals fulfilling the criteria for the Metabolic Syndrome." (PMID 29247377, 2018).
Myocardial fibrosis (2 papers, 2020 to 2022). "The same report also provided evidence that CCN5 delivered to the heart by a recombinant adeno-associated virus vector caused apoptosis of activated myofibroblasts in the heart subjected to transverse aortic constriction and attenuated myocardial fibrosis." (PMID 34854055, 2022). "Expression of CCN5 was upregulated after ACEI treatment, which further reversed myocardial fibrosis and protected heart function via inhibition of TGF-β1 signaling and fibroblast-to-myofibroblast transition." (PMID 33013358, 2020).
salivary gland tumors (2 papers, 2015 to 2021). "In salivary gland tumours, WISP-2/CCN5 expression is reduced when compared to normal salivary gland tissue, suggesting that loss of CCN5 may be associated with the development or progression of salivary gland tumours." (PMID 34205668, 2021).
sarcopenia (2 papers, 2022 to 2026). Progressive decline in muscle mass due to aging which results in decreased functional capacity of muscles. "In young mice, CCN5 knockdown induced a sarcopenia-like phenotype, encompassing skeletal muscle dysfunction and myosteatosis (fat mass: p < 0.01; intramyocellular triglyceride: 66.02 ± 3.798 vs. 104.5 ± 8.542 μg/mg tissue, p < 0.01)." (PMID 41944790, 2026). "By comparing gene expression in human skeletal muscle across three stages of sarcopenia, we identified CCN5 as a gene exhibiting decreased protein expression in possible sarcopenia stage (approximately 33% reduction, p = 0.0245), with this decline persisting into sarcopenia stage (p = 0.0093)." (PMID 41944790, 2026).
triple-negative breast carcinoma (2 papers, 2017). An invasive breast carcinoma which is negative for expression of estrogen receptor (ER), progesterone receptor (PR), and human epidermal growth factor receptor 2 (HER2). "We show that, in triple-negative-breast cancer (TNBC) cells enriched with TICs, CCN5 significantly blocks cellular growth via apoptosis, reversing EMT-signaling and impairing mammosphere formation, thereby blocking the tumor-forming ability and invasive capacity of these cells." (PMID 28450698, 2017).
Arrhythmia (1 paper, 2020). Any cardiac rhythm other than the normal sinus rhythm. "In addition, electrophysiological studies revealed a reduction in the incidence of rapid atrial pacing‐induced arrhythmias by AAV9‐mediated CCN5 gene transfer and in CCN5 Tg mice." (PMID 32885578, 2020).
autoimmune disease (1 paper, 2021). A disorder resulting from loss of function or tissue destruction of an organ or multiple organs, arising from humoral or cellular immune responses of the individual to their own tissue constituents. "Of particular interest, Wnt-1 induced secreted protein-2 (WISP2/CCN5), which is involved in inflammation response and autoimmune disease, achieved the highest correlation coefficient (Rs = 0.81, p = 2.82e-5)." (PMID 34899357, 2021).
Cholestatic liver disease (1 paper, 2023). "Since pMF play a major role in the setting of cholestatic liver diseases, we next analyzed Ccn5 expression in rat fibrotic livers that were obtained by subjecting animals to bile duct ligation (BDL) for two weeks." (PMID 37166689, 2023).
chordoma (1 paper, 2014). Chordomas are rare malignant tumors arising from embryonic remnants of the notochord in axial skeleton. "Through gene expression analysis, we detected expression of CCN1, CCN2, CCN3 and CCN5 in U-CH1 cells under basal conditions, and demonstrate increased expression of CCN3 and CCN5 by chordoma cells in hypoxia." (PMID 25541962, 2014).
colitis (1 paper, 2022). Inflammation of the colon. "Genes related to promoters differentially methylated uniquely in Dnmt3aΔIEC mice (e.g., Cdkn2c, Ccn5, Ctnnbip1, and Sfrp5) at day 5 after the initiation of DSS colitis were enriched in processes related to cell junction and cell proliferation." (PMID 36271073, 2022).
head and neck cancer (1 paper, 2021). A primary or metastatic malignant neoplasm affecting the head and neck. "Limited evidence exists about the role of WISP-2/CCN5 in head and neck cancer." (PMID 34205668, 2021).
hepatic disease (1 paper, 2023). "Actually, there is very little known about CCN5 biology in hepatic disease and the few previous articles available are somewhat inconsistent." (PMID 37166689, 2023).
Hepatic fibrosis (1 paper, 2023). The presence of excessive fibrous connective tissue in the liver. "This analysis revealed that CCN5 was markedly upregulated during hepatic fibrosis and comparable to collagen type I, α-SMA and TGF-β1 that are well-established markers which are increasingly expressed during hepatic fibrosis." (PMID 37166689, 2023). "In the present study, we analyzed the expression of CCN5/WISP2 in cultures of different types of primary liver cells and in an experimental model of hepatic fibrosis." (PMID 37166689, 2023). "This suggests that the increase of CCN5 expression during hepatic fibrosis might be an intrinsic and complex mechanism that can either block or promote aspects of fibrogenesis in pMF." (PMID 37166689, 2023). "Although we have not tested yet if elevated CCN5 expression during hepatic fibrosis correlates with increased CCN5 serum levels, respective measurements might be diagnostically relevant to estimate the activity, progress or outcome during ongoing hepatic fibrosis." (PMID 37166689, 2023). "Increased expression of CCN5, collagen type I, and α-SMA during hepatic fibrosis was also demonstrated by Western blot analysis." (PMID 37166689, 2023). "In line, a study in which CCN5 was transiently overexpressed in the human hepatic stellate cell line LX-2 showed that elevated expression of CCN5 suppressed Smad2 phosphorylation and expression of α-smooth muscle actin (α-SMA) and collagen type I (Col I), which are hallmarks of liver fibrosis." (PMID 37166689, 2023).
lung adenocarcinoma (1 paper, 2023). A carcinoma that arises from the lung and is characterized by the presence of malignant glandular epithelial cells. "First, we investigated to what extent full-length CCN5 (HHS-CCN5(FL)) or the TSP1 domain of CCN5 (HHS-CCN5(III)) would inhibit phospho-AKT (Ser473) levels in A549 human lung adenocarcinoma cells." (PMID 36529291, 2023).
lung diseases (1 paper, 2025). "The review also contrasts CCN5 with other CCN members implicated in fibrotic lung diseases and situates it within broader matricellular signaling networks." (PMID 41939417, 2025).
necrosis (1 paper, 2022). The phenotypic observation that death has occurred in groups of cells or in one or more tissues due to external factors, such as infection, toxins, mechanical trauma, loss of blood supply and other injuries (e.g. corrosion or burning). "This cellular distribution is very similar to that previously observed for CCN2 and other 4-domain CCN proteins during formation of granulation tissue following myocardial necrosis and may point to a role of CCN5 in inhibiting the other 4-domain CCN proteins." (PMID 34854055, 2022).
pancreatic ductal adenocarcinoma (1 paper, 2021). An infiltrating adenocarcinoma that arises from the epithelial cells of the pancreas. "Previously, we have reported that similar to TNBC cell lines, induced overexpression of CCN5 in pancreatic ductal adenocarcinoma (PDAC) cells promotes mesenchymal–epithelial transition (MET) and weakens the steaminess of these aggressive cells." (PMID 33745223, 2021).
renal fibrosis (1 paper, 2021). A final common manifestation of a wide variety of chronic kidney diseases characterized by glomerulosclerosis and tubulointerstitial fibrosis. "Comparable to CCN3/NOV in renal fibrosis, and opposite to fibrotic CCN2/CTGF, CCN5/WISP-2 is anti-fibrotic in the heart." (PMID 34063397, 2021).
retinoblastoma (1 paper, 2019). A malignant tumor that originates in the nuclear layer of the retina. "A series of canonical pathways, including those involved in Rb (Retinoblastoma)/E2F cell cycle (Rb, E2f2, E2f3, E2f5, Cdk6, DHFR), Notch (Dll1, Notch 2, Jag1), Wnt (Wnt, Axin2, Wisp2/Ccn5) and NF-κB (Ikbip) were found to participate in this network." (PMID 30742662, 2019).
Testicular atrophy (1 paper, 2025). Wasting (atrophy) of the testicle (the male gonad) manifested by a decrease in size and potentially by a loss of fertility. "In aged mice, CCN5 knockdown improved testicular atrophy, restored lipid droplet content and testosterone synthesis, and enhanced physical endurance and sexual behavior." (PMID 40756763, 2025).
tumor (40 papers, 2004 to 2025). "For instance, it was previously reported that high CCN5 expression level was associated with less frequent disease progression and suppressed invasive phenotypes of tumor cells, indicating a potential role as a tumor suppressor." (PMID 39144722, 2024). "CCN5 expression is lowered in HCC tumor tissues compared with normal tissue, while contrarily high CCN5 expression was associated with better prognosis in HCC, suggesting a dual role in CCN5 activity." (PMID 37166689, 2023). "The action of EGCG against CCN5 results in the decrease of cell viability, diminishment of sphere-forming ability and suppression of tumor growth in vivo in TNBC cells." (PMID 37838685, 2023). "EGCG enhances the activity of CCN5 by improving its bioavailability and enhancing its anti-tumor properties." (PMID 37838685, 2023). "CCN5 was shown to inhibit tumor progression at least in part by inhibiting the expression of genes involved in the TGF-β signaling cascade." (PMID 35696413, 2022). "For example, CCN5 functions as a transcriptional co-repressor that down-regulates expression of the TGF-β receptor II in human tumor breast tissues." (PMID 35476850, 2022). "CCN5 is a tumor suppressor, which restored ER-α expression at the transcription level via integrins-α6β1/Akt/FOXO3a signaling activation in breast cancer." (PMID 33833779, 2021). "EGCG upregulates CCN5 expression in the tumor and effectively delays tumor growth in the human TNBC xenograft model." (PMID 34948368, 2021). "CCN5 acts as a tumor suppressor in the Erα-positive cell line by binding to the promoter of TGF-β in the nucleus to suppress its expression." (PMID 34940056, 2021). "Based on these encouraging in vitro observations, we were intrigued to know the effect of CCN5 on SP cell-mediated tumor growth." (PMID 28450698, 2017). "For further corroboration of the antitumorigenic role of CCN5 in TNBC, we determined the effect of CCN5 treatment in CSCs/TICs status, which is responsible for tumor initiation, development and also recurrence of the disease." (PMID 28450698, 2017). "We also observed that CCN5 treatment or overexpression in SP cells significantly impairs in vitro growth, migration and tumor forming ability in xenograft model." (PMID 28450698, 2017). "This indicated that CCN5 has a role as a tumour suppressor gene." (PMID 40016720, 2025). "However, its expression decreases in invasive BC and in adjacent invasive foci, with the level of CCN5 also decreasing as tumour differentiation worsens, leading to very low expression in poorly differentiated tumours." (PMID 40016720, 2025). "Emerging evidence suggests that CCN5 may act as a tumor suppressor by inhibiting epithelial-mesenchymal transition (EMT), a critical step in cancer metastasis." (PMID 39144722, 2024). "Notably, a previous study showed that CCN5 functions as a transcriptional repressor during regulation of TGF-β receptor II expression in human tumor breast tissues." (PMID 35476850, 2022). "Subsequently, the consistent role of CCN5 in tumor suppression was also reported by others." (PMID 33745223, 2021). "CCN5 acts as a tumor suppressor/anti‐invasive protein in TNBC." (PMID 33745223, 2021). "CCN5 is downregulated in human leiomyoma, pancreatic adenocarcinoma, salivary gland cancer, colorectal tumors, and gallbladder cancer, suggesting that it acts as a tumor suppressor." (PMID 33833779, 2021). "Exertion of anti-tumor activity of EGCG (DB12116) is inferred to be mediated by CCN5." (PMID 34940056, 2021). "All these factors contribute to the tumor‐suppressive properties of CCN5 against BC." (PMID 33745223, 2021). "In most studies, CCN5 expression has been shown to correlate inversely with the aggressiveness of cancers in breast, pancreas, salivary gland, gallbladder and gastric tissue, suggesting tumor suppressor/anti-invasive activity." (PMID 29370782, 2018).